FTH1P11 (ferritin heavy chain 1 pseudogene 11)
Synonyms: formerly FTHL11
Gene: Processed pseudogene on chromosome 8 (81,521,682 to 81,522,232, reverse strand). Ensembl gene ENSG00000237264.
Diseases named in the same sentence as FTH1P11 in open-access papers:
FTH1P11 is named in the same sentence as 3 diseases in open-access papers, as found by Europe PMC text mining. Sharing a sentence is not in itself a finding about the gene and the disease. The quoted sentences say what the papers report.
prostate carcinoma (2 papers, 2019 to 2020). A carcinoma that arises from epithelial cells of the prostate gland. "In DU145 and PC3 models of prostate cancer FTH1 and FTH1P11 and FTH1P16 show near equimolar expression level, further underlining the fulfilment of an important criterion for an effective parental gene:pseudogene ceRNA network." (PMID 33260500, 2020). "The FTH1 query also resulted in the identification of pseudogenes (FTH1P2, FTH1P8, FTH1P11, FTH1P16) that regulate FTH1 in prostate cancer as well novel miRNAs that may be involved in ceRNA network regulation of FTH1 in prostate cancer." (PMID 31029062, 2019). "Interestingly, in DU145 and PC3 models of prostate cancer, the addition of iron induced the expression not only of FTH1, but also of FTH1P11 and FTH1P16, two pseudogenes whose expression is not regulated by IREs, while iron depletion down-regulated FTH1, FTH1P11, and FTH1P16." (PMID 33260500, 2020).
FTH1P11 also shares sentences with these, for which no sentence is quoted: bacterial meningitis (1 paper); lung adenocarcinoma (1).